AHR (aryl hydrocarbon receptor)
Diseases named in the same sentence as AHR in open-access papers (continued):
Sharing a sentence is not in itself a finding about the gene and the disease.
tumor (continued). "Inhibition of AhR in myeloid cells reduced PDAC growth due to increased infiltration of IFNγ + CD8 + T cells in murine PDAC tumor." (PMID 36139638, 2022). "Conversely, Sox9 (a Wnt and Yap1-target gene) and some canonical targets of Yap/Tead such as Cyr61 and IL33 which have known roles in stem cell maintenance, cell migration and tumor invasiveness - were repressed by AHR." (PMID 35383166, 2022). "Tumor incidence reached close to 45% in AhR-null mice but remained below 20% in AhR wild type animals." (PMID 35619220, 2022). "We further show that microbiome-derived formate drives CRC tumour invasion by triggering AhR signalling, while increasing cancer stemness." (PMID 35437333, 2022). "For example, tumors derived from this cell line exhibit T cell exhaustion and two AhR-active tryptophan -related metabolites, indoxyl sulfate and indole propionic acid inhibited tumor growth." (PMID 36428667, 2022). "Gut microbiome-derived indole-3-propionate partially activates the AhR on macrophages to induce an M2-like phenotype, similar to the macrophage phenotype in the tumor microenvironment." (PMID 36613754, 2022). "On the one hand, it can lead to accumulation of Kyn and consequent activation of the KAT reaction of Kyn → KA, thereby enhancing AhR activity to the advantage of tumours." (PMID 36286592, 2022). "An important feature of cancer biology is the identification of IL-4I1 (L-Phe oxidase) as a metabolic immune checkpoint that activates the AhR and promotes tumour progression by enhancing cancer cell motility and suppressing adaptive immunity." (PMID 36286592, 2022). "The mechanisms by which IDO1 and kynurenine metabolites promote tumorigenesis include the shaping of a tumor-friendly immune microenvironment and the activation of aryl hydrocarbon receptor." (PMID 35903691, 2022). "Kynurenine, a ligand for the aryl hydrocarbon receptor (AHR), suppresses T cells’ anti-tumor response." (PMID 36072596, 2022). "IL4I1 inhibited the proliferation of T cells including CD8 + anti-tumor T cells and recruited suppressor immune cells such as Tregs by activating Aryl hydrocarbon receptor (AHR)." (PMID 36118894, 2022). "AHR is involved in the formation of tumors as its activation enhanced clonogenic survival and motility of tumor cells and as transgenic mice with a constitutively active AHR spontaneously develop tumors." (PMID 35371054, 2022). "Along this line, a first approach has consisted in defining in each tumor type an AhR-specific genetic signature to score it and assess its prognostic value." (PMID 35681770, 2022). "AHR promotes tumor development by sustaining cell stemness through Jak/Stat3, detoxifying effects of benzo[a]pyrene and regulating CYP1B1 enzyme." (PMID 36499247, 2022). "Kyn produced by CAFs participated in the activation of AhR signals in tumor cells, thereby resulting in the downstream AKT/ERK signals activation." (PMID 35831824, 2022). "Aggressive malignancies harbor higher expression of AhR, the latter constitutively translocates to the nucleus, suggesting its role in tumor progression." (PMID 35173722, 2022). "Metabolite kynurenine inhibits T-cell infiltration and induces PD-1 expression by activating the aryl hydrocarbon receptor (AHR) to promote tumor progression." (PMID 36231064, 2022). "The activation of the aromatic receptor AHR by tryptophan catabolites can enhance malignancy of a tumor and inhibit anti-tumor immunity." (PMID 36407768, 2022). "For example, the intestinal microbiome–metabolite formate drives CRC tumor invasion via triggering AhR signaling while increasing cancer stemness." (PMID 36583106, 2022). "Since the Kyn-AHR axis inhibits the functions of T cells, the inhibition of Trp-catabolic enzymes also restricts the occurrence and development of tumor." (PMID 33692337, 2021).
tumor (continued). "Recently, it has been shown that 5-hydroxytryptophan induced AhR activation of tumor-infiltrating CD8+ T cells induces a downregulation of cytokines and effector molecules rendering T cells exhausted and dysfunctional in the tumor microenvironment." (PMID 34135898, 2021). "TDO2 promotes tumor progression through the production of kynurenine, which is an endogenous ligand of the aryl hydrocarbon receptor (AHR), known to be involved in increased tumor cell survival and motility, and reduced anti-tumor immune responses." (PMID 34943977, 2021). "Despite the absence of recurrent genetic abnormalities in cancer, the level of AhR mRNA is elevated in almost 70% of various tumor types relative to healthy tissue." (PMID 33451095, 2021). "AhR in an autocrine/paracrine manner can inhibit the anti-tumor immune response and promote tumor cell survival and movement." (PMID 34458309, 2021). "Studies on various tumor types and tumor cell lines have shown high AhR expression, suggesting that AhR is activated constitutively by specific ligands in tumors and facilitates their growth or immune evasion." (PMID 33924971, 2021). "TNF-α has been shown to suppress cellular responses to AhR activation and has been considered as an anti-tumor cytokine owing to its strong cytotoxic effects on some tumor cells in vitro." (PMID 33961948, 2021). "Although, this effect was obtained in a KP-independent mechanism, further research is still needed to reveal if any of TRP metabolites have a tumor suppressive role through AhR activation." (PMID 34071442, 2021). "Various antagonists have been tested to lower the level of AhR expression in the tumor when it has an oncogenic function." (PMID 33451095, 2021). "In conclusion, our study described a novel mechanism, in which TDO2 mediated the Trp metabolism and activation of the Kyn/AhR/IL-6 signaling pathway in tumor cells." (PMID 34657635, 2021). "And the Kyn produced by Trp catabolizing enzyme IDO in tumor cells has been demonstrated to facilitate AhR activation and tumor growth in an immune independent manner." (PMID 34657635, 2021). "In NOD-SCID mice with SMC-7721 tumors, both chemotherapeutic DOX and AhR inhibitor PDM2 resulted in tumor suppression and prolonged overall survival." (PMID 34657635, 2021). "There is considerable evidence indicating the contribution of constitutively active AHR during pro-proliferative effects; moreover, the expression level of AHR is notable in tumor staging and malignancy." (PMID 34576152, 2021). "For instance, Kynurenine, the catabolic product of tryptophan, induces the invasion of cancer cells and immunosuppression of the tumor microenvironment by binding to transcription factor aryl hydrocarbon receptor." (PMID 34659216, 2021). "Specifically, in tumor cells, emerging evidence suggests a promoting role for AhR in the initiation, promotion, progression, invasion, and metastasis of cancer cells." (PMID 33924971, 2021). "Three major points need to be addressed to efficiently modulate AhR activity for the treatment of neoplastic diseases." (PMID 33451095, 2021). "AHR is involved in carcinogenesis in various cancers, influencing all major stages of tumor development, i.e., initiation, progression, and metastasis formation." (PMID 34075438, 2021). "AhR activity was significantly increased in tumor group of ESCA, HNSC and THCA, while decreased in tumor group of BLCA, BRCA, COAD, KICH, KIRP, LIHC, LUAD and PRAD." (PMID 34290693, 2021). "Contrary to what was initially believed, AhR is not only a toxicant-related transcription factor, but also plays a crucial role in the tumor immune microenvironment." (PMID 34290693, 2021). "Thirty-two tumours (58%) showed a high expression of AhR, and 19 of these (95%) belonged to the PDTC/ATC group (p < 0.001)." (PMID 34640369, 2021).
tumor (continued). "It has been found that the AhR signaling pathway is able to regulate the growth, migration, and invasion of tumor cells, and the activation state of AhR plays an important role in the immunotherapy of certain kinds of tumors." (PMID 34955744, 2021). "An overexpression of CYP1B1 and AhR has also been observed in inflammatory breast cancer (IBC) which correlated significantly with tumour grade, lymphovascular invasion, metastatic lymph nodes and the expression of Ki67 indicating cell proliferation." (PMID 33809117, 2021). "Under these conditions, Kyn bound to tumor cell aryl hydrocarbon receptor (AhR) and supported cancer cell survival." (PMID 34832904, 2021). "Kyn activates the aryl hydrocarbon receptor (AhR) which contributes to cancer immune escape since it promotes an immunosuppressive tumor microenvironment by an increase of IL-10, Treg cells and suppressing immune activation cells." (PMID 33466323, 2021). "Among them, the aryl hydrocarbon receptor (AhR) signaling pathway is closely related to tumor cell migration." (PMID 34955744, 2021). "HIF-1α and AHR modulate the metabolism of neoplastic and immune cells to impact tumor immunity and progression." (PMID 34712225, 2021). "Several studies have shown that PTC reduces cell proliferation (GH3 tumor cells) and inhibits the basal activity of the aryl hydrocarbon receptor (AhR)." (PMID 33672042, 2021). "Acting as an agonist at AhR, a transcription factor for several genes places Kyn-AhR axis to serve immunomodulatory role as AhR signaling is critical for immune tolerance, tumor evasion, cell adhesion and migration." (PMID 34205235, 2021). "Kyn derived from tumor cells has been shown previously to mediate the activation of AhR signals, thus contributing to immunosuppressive effects in T cells." (PMID 34657603, 2021). "Meanwhile, elevated expression of c-Myc was found in Kyn treated tumor cells, and suppression of AhR inhibited the expression of c-Myc." (PMID 34657603, 2021). "While this study focused on the direct impact of AhR on tumor cells, the differential effect of AhR ligands on the Treg/Th17 balance depending on the dietary context cannot be excluded." (PMID 33801480, 2021). "IDO1 also suppresses anti-tumor responses through the generation of L-kynurenine, an endogenous agonist of the arylhydrocarbon receptor (AhR)." (PMID 33747948, 2021). "The aryl hydrocarbon receptor Ahr, on the other hand, can either suppress or promote tumor development depending on the cell phenotype." (PMID 34439225, 2021). "One area that remains controversial is the role of AHR signaling in colorectal and other GI cancers, since AHR is shown to have both pro- and anti- apoptotic and tumor suppressor properties." (PMID 34149693, 2021). "Although the impact of AhR expression on carcinogenesis is difficult to characterize, its activation by diverse ligands and the role of various cofactors are important for determining how AhR influences tumor development and phenotype." (PMID 33451095, 2021). "Mechanistically, we found that AhR expression contributed to the secretion of Interleukin-6 (IL-6), thereby promoting tumor cells proliferation through the STAT3 and NF-kB/TIM4 signals." (PMID 34657635, 2021). "New treatment options targeting IDO1, TDO2 and the AHR 35 are currently tested in clinical trials in diverse tumor entities." (PMID 34646367, 2021). "L-KYN has been reported to support the regulatory T-cells and tumor formation through the AhR as well as the activation of the adenylate- and guanylate-cyclase pathways." (PMID 34202246, 2021). "Despite these complexities, the role of AhR in therapeutics for tumor suppression is under intense investigation." (PMID 33916690, 2021). "They thus reinforce the interest of analyzing both the level of AhR expression and the correlated transcriptional signature to define specific anti-tumor strategies." (PMID 33451095, 2021).
tumor (continued). "Kynurenine-AhR-dependent signalling is implicated in TME immunosuppression by promoting Treg differentiation and driving the recruitment of immunosuppressive tumour-associated macrophages to the TME." (PMID 34944851, 2021). "Activation of AhR by kynurenine has also been reported to inhibit the growth of tumor cells, promote cellular differentiation, and decrease the formation of hepatic and pulmonary metastases in mice through activation of the tumor suppressor gene KISS1." (PMID 33451095, 2021). "Consistently, activation of AhR/IL-6/STAT3/ NF-kB signaling was observed in TDO2 overexpression tumor tissues." (PMID 34657635, 2021). "AHR expression was also elevated in primary tumor sections obtained from AFB1-HCC patients, which paralleled the upregulation of PD-L1, a clinically relevant immune regulator." (PMID 34373448, 2021). "Kynurenine, which is the catabolic product of tryptophan, induces the invasion of cancer cells and the immunosuppression of a tumor microenvironment by binding to transcription factor aryl hydrocarbon receptor (AHR)." (PMID 34804978, 2021). "In this regard, AhR inhibition in combination with anti-PD-1 antibody significantly reduced tumour growth and improved survival compared to either treatment alone in these models." (PMID 34944851, 2021). "Kyn drives tumor escape by acting as a ligand and constitutively activating AhR to express genes involved in cell-growth." (PMID 33916690, 2021). "Median expression of AhR appears elevated from stage I, independently of the tumor type, suggesting that this increased expression is an early event in many cancer." (PMID 33451095, 2021). "Specifically, expression of AhR increases in mammary tissue during tumor progression with expression of AhR gene targets and inflammatory markers (e.g., COX-2 and C/EBPβ) increasing accordingly." (PMID 33763068, 2021). "The TRP degradation pathway plays an influential role in cancer biology via indoleamine 2,3-dioxygenase (IDO), where KYN acts as a ligand for an aryl hydrocarbon receptor (AhR) to promote tumor progression and metastasis." (PMID 33615198, 2021). "We explored the role of AhR in tumor cell lines and patients using genomic data sets and discuss the extent to which AhR can be considered as a therapeutic target." (PMID 33451095, 2021). "AHR activation by tryptophan catabolites promotes tumor malignancy and suppresses anti-tumor immunity, thereby promoting tumor progression." (PMID 34784845, 2021). "It should be noted, however, that such a tumor suppressor function has been mostly described in mice, underscoring the specificity of AhR function between species." (PMID 33451095, 2021). "The expression of a large number of genes significantly correlated (p < 0.001) with AhR mRNA levels across tumor types, in particular those in the lung and brain." (PMID 33451095, 2021). "The comprehensive investigation of differences in AhR expression between normal and tumor tissues led the discovery of the potential immunotherapeutic value of AhR in various tumors." (PMID 34290693, 2021). "It was previously shown, that IL-6 expressing MCF-7 are characterized by the EMT phenotype and an increased metastatic potential, so in linking these two reports it is proper to consider KYNA/AhR interaction as a factor enhancing tumor invasiveness." (PMID 34071442, 2021). "Aryl hydrocarbon receptor (AHR) was considered to be an important pan-tumor therapeutic target, but small molecule inhibitors targeting AHR target gene IDO1 have failed in clinical trials." (PMID 33692337, 2021). "Meanwhile, AhR expression was significantly correlated with tumor stage of some cancers, including BLCA, KIRP, and STAD." (PMID 34290693, 2021). "This is in the line with a few other reports, which shows that AhR acts like a tumor suppressor in liver cancer, colorectal cancer, melanoma, and prostate cancer." (PMID 34071442, 2021).
tumor (continued). "The TDO-induced KYN represses the body’s anti-tumor immune response, thereby promoting tumor cells motility and survival through the AhR system." (PMID 34202246, 2021). "Aryl hydrocarbon receptor (AhR) activation by kynurenine results in the generation of immune-tolerant dendritic cells and regulatory T cells, which foster a tumor immunological microenvironment." (PMID 34608122, 2021). "Such a correlation analysis makes it possible to identify, among already available molecules, those that are adapted to the tumor type according to AhR level." (PMID 33451095, 2021). "KYN is secreted by tumor cells and is further described to serve as a ligand for the cytoplasmic AhR of CD8+ T-cells, thereby inducing PD-1 expression and immune surveillance." (PMID 33211154, 2021). "IDO is highly expressed in tumor cells, and kynurenine acts as a ligand for the aryl hydrocarbon receptor (AhR), regulates the transcription of various genes, and inhibits T cell function, resulting in the suppression of the immune system." (PMID 34209281, 2021). "In cancer cells, a main purpose of TRP metabolism through IDO is to produce KYN for suppression of antitumor immune T cells via AhR signaling, thus creating a suitable tumor microenvironment that indirectly leads to increased growth." (PMID 33615198, 2021). "The aryl hydrocarbon receptor (Ahr) is a transcription factor with known roles in tumor progression and dissemination in different tissues and organs." (PMID 34439225, 2021). "Snail, a well-known EMT-promoting transcription factor, is a potential target gene under AhR regulation shown to suppress E-cadherin expression during tumor metastasis." (PMID 34769098, 2021). "Mechanistically, GBM tumour cell kynurenine production activates the aryl hydrocarbon receptor (AHR) on TAMs, decreasing NFKβ signalling and thereby promoting an M2-like phenotype, leading to cytotoxic CD8+ T cell dysfunction." (PMID 34944870, 2021). "Results from analyses of the tumor microenvironment revealed the regulation of PD-1 expression by the intracellular AhR." (PMID 33211154, 2021). "Our results showed the expression of AhR predominately located in the nucleus of tumor cells in LSCC." (PMID 34941188, 2021). "Because the role of AhR in cancer is complex, we propose to tailor the AhR therapeutic strategy by considering the level of AhR expression (high/low) (and its correlated gene-signatures that are specific to tumor types and patients." (PMID 33451095, 2021). "Following activation, both AhR and β-catenin translocate to the cell nucleus where they play tumor-promoting roles." (PMID 34769098, 2021). "Meanwhile, Wnt5α was also reported to mediate IDO1 activity via a β-catenin dependent signaling pathway in dendritic cells, and facilitate the IDOs activation through the AhR-IL-6-STAT3 signaling loop in several tumor types." (PMID 34657603, 2021). "Upon activation by its natural endogenous agonist, KYN, AHR translocates into the nucleus and regulates target gene expression in T cells, including a tumor-promoting role via suppression of anti-tumor immunity." (PMID 34025677, 2021). "Natural substances, such as dietary flavonoids, polyphenols found mostly in fruit, vegetables, and other plant sources, have been largely studied for their beneficial role in inhibiting tumor development through the control of AhR activity." (PMID 33451095, 2021). "Clinical parameters, including patient age, gender, survival, and tumor stage were analyzed to assess the prognostic value of AhR." (PMID 34290693, 2021). "A higher expression of AhR was found in PTC infiltrating the airway compared to intrathyroid tumours (50% of PTC-A vs. 33% of PTC-B)." (PMID 34640369, 2021). "Tumor‐specific AhR (n=920) and aromatase levels (n=816) were evaluated on tissue microarrays using immunohistochemistry." (PMID 34094928, 2021).